NUPR1 (nuclear protein 1, transcriptional regulator)
Diseases named in the same sentence as NUPR1 in open-access papers (continued):
Sharing a sentence is not in itself a finding about the gene and the disease.
cancer (continued). "Gene inactivation of NUPR1 in different cancer cell lines, such as PDAC, hepatocarcinoma, glioblastoma, multiple myeloma, osteosarcoma, and non-small lung cancer, has been shown to halt tumor growth." (PMID 41249113, 2025). "Studies have shown that ZZW-115 enhances cancer cell sensitivity to genotoxic agents by obstructing NUPR1’s nuclear translocation, decreasing the SUMOylation-dependent functions of DNA damage proteins." (PMID 38802795, 2024). "In this study, we showed that NUPR1 overexpression upon acquisition of DOX resistance leads to upregulation of cancer-promoting signaling." (PMID 38536720, 2024). "NUPR1, a highly expressed protein in cancer cells, is activated in response to stress signals, including oxidative stress, playing a pivotal role in regulating redox processes." (PMID 39456519, 2024). "While discontinued, we have presented evidence that low doses of reserpine can suppress TEV-mediated cancer progression in TNBC murine mouse models by altering NUPR1 expression." (PMID 38405101, 2024). "NUPR1 influences cancer cell resistance and promotes the proliferation of cancer cells bypassing the G0/G1 check point." (PMID 38536720, 2024). "The expression of NUPR1 in high‐grade BLCA was significantly higher than that in low‐grade cancer (p < 0.01)." (PMID 36468653, 2023). "NUPR1 was involved in several cancer‐related processes, such as apoptosis, autophagy, cell cycle, and metastasis." (PMID 36468653, 2023). "It was found that HUVEC cells cultured with cultures of si-NUPR1-transfected cancer cells showed a significant reduction in tube formation activity and inhibition of VEGFA expression." (PMID 37854285, 2023). "The stress response molecule nuclear protein‐1 (NUPR1) is essential for the growth of multiple types of human malignant tumor cells." (PMID 37854285, 2023). "NUPR1 (Nuclear Protein 1) is a stress-inducible protein that is expressed in most cancer cells and is involved in several cellular processes including the regulation of cell cycle and therapeutic resistance." (PMID 35406596, 2022). "NUPR1 protected cancer cells from ferroptosis, one of oxidative cell death, by participating in iron metabolism." (PMID 36258210, 2022). "Recently, NUPR1 has been demonstrated to impact ROS production and redox homeostasis in multiple types of cancers." (PMID 36258210, 2022). "NUPR1 is a stress-inducible nuclear protein that responds to cellular stress and features cancer initiation and development properties." (PMID 36307402, 2022). "NUPR1 is widely reported to act as an oncogene in several types of cancers and regulates a series of downstream genes via interacting with transcription factors." (PMID 36258210, 2022). "Nuclear protein‐1 (NUPR1) plays a role in promoting the proliferation of cancer cells by influencing cell cycle progression." (PMID 36400857, 2022). "To preliminarily investigate the transcriptional expression level of NUPR1 in cancers, we analyzed a TCGA pan-cancer cohort." (PMID 36307402, 2022). "In this line, our recent studies have shown that ZZW-115, a powerful inhibitor of NUPR1, is able to kill cancer cells from different tumors, including PC." (PMID 34067040, 2021). "Increasing evidence suggests that the inactivation of NUPR1 impairs mitochondrial function and energy metabolism in cancer cells, increases ROS levels, and triggers a variety of cell death pathways, including apoptosis, autophagy, and necroptosis." (PMID 34359572, 2021). "The inactivation of NUPR1 in cancer cells can trigger ROS overproduction by inducing mitochondrial dysfunction, thereby leading to cell death." (PMID 34359572, 2021). "One important process in cancer cells allowing the formation of drug resistance and heterogeneity is the upregulation of NUPR1 expression." (PMID 34359572, 2021). "The therapeutic potential of genetic or pharmacological inhibition of NUPR1 in cancer is also discussed." (PMID 34359572, 2021).
cancer (continued). "In this context, Liu and colleagues showed in cancer cells that NUPR1 can regulate iron metabolism through transcriptional activation of lipocalin 2 (LCN2) and protect the cells from ferroptosis." (PMID 34359572, 2021). "NUPR1 is a highly expressed protein that confers drug resistance to cancer cells through the maintenance of redox and the antioxidant system in various pathological conditions." (PMID 34359572, 2021). "NUPR1 has been studied as a new target for various cancers since its discovery as it affects cell growth, migration, and invasion." (PMID 33920455, 2021). "NUPR1 mRNA levels were significantly increased in ccRCC cells and cancer tissues compared with HK-2 cells (human renal cortex/proximal tubular epithelial cells) and adjacent normal kidney tissues." (PMID 34030133, 2021). "The elucidation of the translocation mechanism of NUPR1 is expected to provide important information concerning the resistance of cancer drugs and their extrinsic cytotoxicity." (PMID 33801927, 2021). "In this study, we assessed NUPR1 expression in cancer cell lines, clinical ccRCC samples and adjacent kidney tissue." (PMID 34030133, 2021). "We provide arguments favoring the targeting of NUPR1 to induce ferroptosis as a therapeutic strategy for treating cancer." (PMID 34359572, 2021). "In this work, we sought to use an indirect design to obtain new compounds targeting the totally unstructured tumorigenic protein NUPR1, building on former successful efforts that had led to the identification of the anti-cancer drug ZZW-115." (PMID 34680086, 2021). "The NUPR1 thereby promotes the transformation of healthy cells into cancer cells as a protective mechanism against oxidative stress." (PMID 34359572, 2021). "On the other hand, as an important transcription factor, NUPR1 can regulate the redox reaction for cancer initiation and development." (PMID 34359572, 2021). "Methamphetamine (METH)-induced ER stress has been shown in non-cancer cells to initiate apoptosis and autophagy via the NUPR1/CHOP/TRIB3 pathway." (PMID 34359572, 2021). "One such potent inhibitor of NUPR1 is ZZW-115, which causes mitochondrial damage, energy metabolism deregulation, and ROS overproduction in a variety of cancer cells." (PMID 34359572, 2021). "Since targeting NUPR1 by ZZW-115 is highly efficient for treating cancers, it became essential to determine the molecular mechanisms by which ZZW-115 exerts its antitumoral activity and eventually to determine other anticancer-associated functions." (PMID 32780723, 2020). "We propose that ZZW-115 sensitizes cancer cells to genotoxic agents by inhibiting the nuclear translocation of NUPR1 and thereby decreasing the SUMOylation-dependent functions of key proteins involved in the DDR." (PMID 32780723, 2020). "We have described the interaction between the NLS region of NUPR1, a nuclear intrinsically disordered protein involved in cancer, and Impα3 by using a series of peptides comprising that polypeptide patch." (PMID 32933064, 2020). "The ZZW-115-dependent inhibition of NUPR1 nuclear translocation sensitizes cancer cells to genotoxic agents by affecting SUMOylation." (PMID 32780723, 2020). "NUPR1 is upregulated in response to stress and has a promoting effect on cancer cell metastasis and resistance to therapy." (PMID 31941933, 2020). "For example, Nuclear protein 1 (NUPR1) is a molecule regulated in response to stress, that has been implied in the progression of many cancers including of breast, pancreas, brain, and thyroid, in the development of metastasis." (PMID 33194736, 2020). "It is interesting to note that NUPR1 has been reported to play different roles before cancer development, during cancer progression and in response to cancer treatment." (PMID 33008348, 2020). "Several empiric observations have shown that cancer cells undergo growth arrest or cell death after genetic inactivation of NUPR1 in vitro and in vivo." (PMID 30451898, 2018).
cancer (continued). "In this regard, after NUPR1 inhibition we observed a mitochondrial metabolism failure and mitochondrial dysfunctions and cancer cells switch on glycolysis for energy production." (PMID 30451898, 2018). "This cascade of processes promotes programmed cell death, what makes NUPR1 and interesting target for cancer treatment." (PMID 30451898, 2018). "Nupr1 was first identified as a gene induced in pancreatitis, but has since then been found over-expressed in several types of cancer and pathological conditions." (PMID 28694771, 2017). "Another recent study showed that Nupr1 can regulate autophagy via mTOR signaling pathway in cancer cells." (PMID 28694771, 2017). "Of note, expression of NUPR1 (a transcription factor involved in progression of liver and other cancers) was about 8-fold increased in our UCHL1 knockdown (p = 1.20x10-8)." (PMID 28472177, 2017). "The KD of NUPR1 was shown to inhibit both cell proliferation and migration and resulted in a cell cycle arrest in more than one cancer types." (PMID 29088719, 2017). "Decreased Nupr1 expression is accompanied by suppression of cancer cell growth in vitro and in vivo." (PMID 27031958, 2016). "Our current reveals an important role of Nupr1 in inhibiting growth of tumorigenic cancer cells in vitro and in vivo and the pathway that is critical for Nupr1 expression." (PMID 27089143, 2016). "Nuclear protein 1 (Nupr1), a small chromatin protein, has a critical role in cancer development, progression and resistance to therapy." (PMID 24902898, 2014). "NUPR1, a small chromatin protein, plays a critical role in cancer development, progression, and resistance to therapy." (PMID 25056123, 2014). "NUPR1 is a phospho-protein that inhibits apoptosis and promotes cell growth, and is over expressed in cancer cells." (PMID 25234738, 2014). "A number of cancer-related genes are located in these two RARs: NUPR1, MVP, MAPK3, FUS, and PYCARD are located in RAR-G12 while ERBB2, GRB7, and PPP1R1B are located in RAR-G13." (PMID 22938721, 2012). "Among these potential cancer-related genes, Nupr1 is known to interact with various molecules involved in cell cycle regulation, programmed cell death and transcription activity." (PMID 22938721, 2012). "We demonstrated that NUPR1 is a promising target for the treatment of different types of cancers." (PMID 41249113, 2025). "ZZW-115 can affect the LLPS process of NUPR1 and prevent the presence of its related SGs, thereby triggering caspase 3 activation, DNA fragmentation, and the formation of apoptotic bodies, leading to cancer cell death." (PMID 40231263, 2025). "NUPR1 plays a crucial role in conferring resistance to ferroptosis in cancer cells." (PMID 38802795, 2024). "Upregulation of NUPR1 and H2BC5 genes has been associated with various cancer types." (PMID 39285481, 2024). "However, intriguingly, our real-world cohort study revealed that, in contrast to mRNA expression, NUPR1 accumulates in cancerous tissues, contributing to the malignant progression of cancer, which necessitates further investigation." (PMID 38167084, 2024). "Therefore, NUPR1 acts as a key regulator of ferroptosis, contributing to ferroptosis resistance in cancer cells by modulating iron metabolism and enhancing antioxidant-related gene expression." (PMID 38802795, 2024). "Cancer cells endure and adapt to various types of stressful environments over prolonged periods, leading us to speculate that NUPR1 mRNA may be consumed more in cancerous tissues compared to adjacent tissues." (PMID 38167084, 2024). "NUPR1 gene plays a variety of roles in benign and malignant tumors." (PMID 37124501, 2023). "NUPR1 was mainly chromogenic in the nucleus of normal tissues adjacent to cancer." (PMID 36468653, 2023). "By identifying trifluoroperazine as a readily translatable repurposed drug inhibitor of NUPR1, we have highlighted a clinical pathway that may improve the treatment of this currently incurable cancer." (PMID 37878712, 2023).
cancer (continued). "NUPR1 is located in the nucleus of various cells, including cancer cells." (PMID 37626099, 2023). "We found that the expression of NUPR1 in high‐grade BLCA was higher than that in low‐grade cancer." (PMID 36468653, 2023). "Interestingly, increased intracellular calcium was shown to induce nuclear transcription of NUPR1, a promoter of cancer progression." (PMID 35756609, 2022). "NUPR1 has been involved in the development of multiple types of cancers." (PMID 35565312, 2022). "In addition, NUPR1 can be activated by some anti-cancer agents, thereby conferring drug resistance to the targeted tumors." (PMID 34359572, 2021). "Therefore, NUPR1 is a crucial factor in the antioxidant system, and its targeting represents a promising strategy for cancer therapy." (PMID 34359572, 2021). "In conclusion, NUPR1 inhibitors have a variety of interesting effects in the treatment of PC, including attenuating fibrosis to slow the PC progression, killing PC cells directly through a variety of ways of death, and fighting drug resistance of cancer cells." (PMID 34067040, 2021). "Understanding the role of NUPR1 in the antioxidant system and the mechanisms behind its regulation of ferroptosis may promote the development of more efficacious strategies for cancer therapy." (PMID 34359572, 2021). "NUPR1 is also a component of the cellular stress response, playing a role in serum starvation, oxidative stress, and drug stimulation, and it is overexpressed in various cancers." (PMID 33801927, 2021). "Thus, we have used a combination of the two approaches to optimize ZZW-115 with the aim of improving its affinity towards NUPR1 and, then, its anti-cancer activity." (PMID 34680086, 2021). "More significantly, collagen/fibronectin could facilitate the activation of PI3K/AKT/SOX2 and CDC42/YAP-1/NUPR1/Nestin signaling pathways via integrin αvβ3, eliciting sustained tumor growth and cancer relapse." (PMID 33408794, 2021). "Therefore, high NUPR1 levels protect against oxidative damage, especially in those cells such as cancer cells with high ROS levels." (PMID 34359572, 2021). "Inhibition of the KPNB1 and NUPR1 interaction may constitute a new cancer therapeutic approach that can increase the drug efficacy while reducing the side effects." (PMID 33801927, 2021). "Therefore, NUPR1 can confer ferroptosis resistance to cancer cells both by enhancing the expression of antioxidant genes and iron metabolism." (PMID 34359572, 2021). "Further studies presenting the development of specific drugs targeting NUPR1 may bring enormous benefits to patients with cancer in the future." (PMID 34359572, 2021). "Notably, NUPR1, which is a transcription factor regulating a complex network of pathways and whose role in various types of cancer including BC has been reported yet remains incompletely understood, was predicted to be most strongly activated." (PMID 34249735, 2021). "Altogether, NUPR1 is a promising therapeutic target in cancer therapy." (PMID 34359572, 2021). "In summary, the observed synergistic cytotoxic effects of doxorubicin–ATZ-502 combination treatment in various cancer cell lines support the hypothesis that nuclear translocation of NUPR1 requires the NUPR1 binding to karyopherin β1." (PMID 33801927, 2021). "Collectively, these results indicate that NUPR1 could be exploited as a target to develop new therapies against cancer, by hindering its protein-protein interactions (PPIs) with other molecular partners." (PMID 34680086, 2021). "Indeed, NUPR1 has attracted attention due to its role in promoting cancer development and progression in the pancreas, as NUPR1-dependent effects also mediate resistance to anticancer drugs." (PMID 31667555, 2020). "We hypothesized, and then proved, that inhibition of NUPR1 by ZZW-115 sensitizes cancer cells to DNA damage induced by several genotoxic agents." (PMID 32780723, 2020).
cancer (continued). "Moreover, the combination of AAV vector-mediated NUPR1 shRNA expression and trifluoperazine (TFP) treatment, an anti-psychotic drug that binds to NUPR1 and is able to mimic NUPR1 deficiency in cancer cells, showed synergistic growth inhibitory activity." (PMID 32674264, 2020). "Importantly, this study now joins several recent studies that have unexpectedly demonstrated favourable results of NUPR1 activation in cancer chemotherapy." (PMID 33041510, 2020). "Then, NUPR1 was found to be over-expressed in many cancer tissues." (PMID 31667555, 2020). "Indeed, NUPR1 has recently elicited significant attention due to its role in promoting cancer development and progression in pancreas." (PMID 31744261, 2019). "Then, NUPR1 was found to be systematically in most of cancer tissues." (PMID 31744261, 2019). "Indeed, NUPR1 has recently elicited significant attention due to its role in promoting cancer development and progression in the pancreas." (PMID 30451898, 2018). "Intriguingly, Nupr1 is a stress-response gene, known to promote cellular survival and senescence through mediation of autophagy, and has primarily been studied in the context of cancer." (PMID 29871632, 2018). "Finally, within the list of upregulated genes in the UCHL1 KD we also found several cancer-associated genes such as SERPINB4, FGF21, NUPR1, SBSN, GDF1, HMOX1, or SOCS2, which suggested the activation of potential compensatory mechanisms in these KDs cells." (PMID 28472177, 2017). "Nupr1 is induced by a variety of stressors and highly expressed in a number of human cancers." (PMID 27285315, 2016). "Our results suggest that Nupr1 is a suppressor of growth of highly tumorigenic TRCs and may have a critical role in cancer progression." (PMID 27089143, 2016). "Downregulation of H4K16ac is likely a mechanism whereby Nupr1 promotes cancer development." (PMID 27285315, 2016). "Induction of Nupr1 is required for cell transformation and cancer development in animal model." (PMID 27285315, 2016). "Induction of Nupr1 is required for cell transformation and cancer development in animal models." (PMID 27285315, 2016). "Moreover, the oncogenic properties of NUPR1, as evidenced by its involvement in promoting cell growth and metastasis in various cancers, indicate that it may serve as a viable biomarker for aggressive tumor behavior and a potential therapeutic target." (PMID 41596413, 2026). "Interestingly, while NUPR1 has been reported to suppress ferroptosis in various cancers by maintaining mitochondrial integrity and iron homeostasis, our previous research demonstrated that NUPR1 knockdown inhibits chondrocyte ferroptosis and delays OA progression." (PMID 40782567, 2025). "Therefore, the level of NUPR1 in cancer cells is correspondingly higher." (PMID 40176685, 2025). "Considering that cancer arises from unregulated and excessive cell division and proliferation, resulting in higher cell density, we hypothesize that NUPR1 expression is relatively elevated in cancer cells characterized by higher cell density compared to adjacent cells with relatively fewer cells." (PMID 38167084, 2024). "This suggests that NUPR1 may be a central regulator of iron metabolism in cancer cells." (PMID 38802795, 2024). "However, our data demonstrated the presence of NUPR1 in cancer cell-derived EVs." (PMID 38405101, 2024). "However, the specific mechanism of NUPR1 in malignant tumors is still unclear." (PMID 36468653, 2023). "However, the influence of NUPR1 on cancer behavior is still unclear." (PMID 36110953, 2022). "Moreover, it is hoped that our results may provide evidence that the regulation of NUPR1 and karyopherin β1 binding may provide a new approach for cancer therapy through drug combination treatment." (PMID 33801927, 2021).